ENSG00000221711
Gene: Small nucleolar RNA gene on chromosome 4 (77,702,746 to 77,702,803, reverse strand). Ensembl gene ENSG00000221711.
Homologues: Orthologues: rat LOC120096422 (78% identical), rat LOC120103353 (76% identical), zebrafish snord75.1 (72% identical), mouse Gm56367 (57% identical).